TET3 (tet methylcytosine dioxygenase 3)
Diseases named in the same sentence as TET3 in open-access papers (continued):
Sharing a sentence is not in itself a finding about the gene and the disease.
type 2 diabetes (7 papers, 2018 to 2024). "TET3 expression was elevated in skeletal muscles of humans with type 2 diabetes and in HFD-fed and ob/ob mice compared with healthy controls." (PMID 38216792, 2024). "Here the authors show that the fetal isoform of HNF4a is induced in mouse livers upon fasting and in type-2 diabetes in a manner regulated by TET3." (PMID 31953394, 2020).
acute myeloid leukemia (6 papers, 2016 to 2022). Acute myeloid leukemia (AML) is a group of neoplasms arising from precursor cells committed to the myeloid cell-line differentiation. "Despite this, we observed a fully penetrant development of B cell lymphomas in all Tet2/3 DKO mice, consistent with our recent finding that acute deletion of Tet2 and Tet3 in hematopoietic stem/ precursor cells results in acute myeloid leukemia." (PMID 27869616, 2016). "But in acute myeloid leukemia, TET3 expression was significantly increased and could be used as an independent prognostic factor." (PMID 36518116, 2022). "TET3, which is aberrantly expressed in acute myeloid leukemia, promotes DNA oxidation." (PMID 31382449, 2019). "TET3 has been recently validated as a miR-150 target in acute myeloid leukemia cells." (PMID 30575719, 2018). "TET3 had been recently identified as a hsa-miR-150 target in acute myeloid leukemia cells." (PMID 30575719, 2018).
Beck-Fahrner syndrome (6 papers, 2021 to 2025). "Beck-Fahrner syndrome is an autosomal dominant disorder with mutations in the catalytic domain to reduce TET3 enzymatic activity." (PMID 39149518, 2024). "Whereas disorders involving writers and readers of DNA methylation have been known for some time, only recently was the first neurodevelopmental disorder impacting the DNA methylation eraser system, TET3 deficiency, or Beck-Fahrner syndrome (BEFAHRS; MIM: 618798), delineated." (PMID 34750377, 2021). "Beck-Fahrner syndrome (BEFAHRS) is the first identified Mendelian disorder of DNA demethylation caused by TET3 deficiency." (PMID 37245029, 2023). "There are no consensus diagnostic criteria for Beck-Fahrner syndrome except modifications to the TET3 gene." (PMID 39149518, 2024). "Beck-Fahrner syndrome (BEFAHRS; OMIM 618798), caused by homozygous, compound heterozygous, or heterozygous mutation in the TET3 gene, is a neurodevelopmental disorder characterized by global developmental delay and variable intellectual disability." (PMID 40469903, 2025). "Here, we observed that ARID2 clustered in a hypermethylation branch close to Beck-Fahrner syndrome (BEFAHRS; TET3) and Kabuki syndrome (KMT2D)." (PMID 40044822, 2025).
endometrial cancer (6 papers, 2017 to 2022). Primary or metastatic malignant neoplasm involving the endometrium (mucous membrane that lines the endometrial cavity). "Here, we demonstrate that OGT and TET3 affect the expression of genes associated with epithelial-mesenchymal transition via changes of histones modifications and the ability of endometrial cancer cells for migration and invasion." (PMID 34948036, 2021). "Analysis of gene expressions in cancer tissue samples from endometrial cancer patients confirmed the association between OGT or TET3 and EMT genes." (PMID 34948036, 2021). "To further investigate whether OGT and TET3 were associated with the expression of EMT genes in endometrial cancer, we analyzed the correlations between these gene expressions in 131 samples of endometrial cancer tissues using quantitative PCR." (PMID 34948036, 2021). "Our results contribute to the knowledge of the role of the TET3/OGT relationship in the complex mechanism supporting endometrial cancer progression." (PMID 34948036, 2021). "Here, we demonstrated that in endometrial cancer cells both TET3 and OGT affected the expression of genes involved in epithelial to mesenchymal transition (EMT), i.e., FOXC1, TWIST1, and ZEB1." (PMID 34948036, 2021). "Thus, the role of TET3 in endometrial cancer seems to be different than TET1 or TET2, and this protein may be involved in modifications of histones by targeting other proteins to chromatin." (PMID 34948036, 2021). "For example, a higher level of TET3 and lower levels of TET1 and TET2 were found in endometrial cancer compared with the normal endometrium, whereas endometrial cancer tissues showed lower levels of global hydroxymethylation at the same time." (PMID 36685517, 2022). "Wound healing and Boyden chamber assays were conducted to evaluate the migration and invasion capacity of endometrial cancer cells with overexpression of OGT and TET3." (PMID 34948036, 2021). "The impact of changes in OGT and TET3 amounts on the expression of genes involved in epithelial-mesenchymal transition (FOXA1, FOXC1, TWIST, ZEB1) in endometrial cancer cells has been analyzed." (PMID 34948036, 2021). "In this study, we analyzed the impact of TET3 and OGT on migration and invasion of endometrial cancer cells via regulation of EMT genes expression." (PMID 34948036, 2021). "In conclusion, our results showed that both TET3 and OGT are involved in the regulation of FOXC1, TWIST1, and ZEB1 in endometrial cancer and affect cancer cell migration and invasion." (PMID 34948036, 2021). "Our results show that both TET3 and OGT affect cell migration and invasion of endometrial cancer cells; however, unexpectedly, their effects are different in HEC-1A and Ishikawa cells." (PMID 34948036, 2021). "Our previous studies showed that TET1 and TET2 messenger RNA expression was lower and TET3 expression was higher in endometrial cancers compared to normal tissues." (PMID 34948036, 2021).
gastric cancer (6 papers, 2016 to 2025). A primary or metastatic malignant neoplasm involving the stomach. "Moreover, curcumin was shown to upregulate the expression of both the TET2 and TET3 enzymes in gastric cancer cell lines, with consequent active demethylation and re-expression of the tumor suppressor RB1." (PMID 41516186, 2025). "This implies that the expression intensity of TET3 protein may serve as an indicator of the malignant level of gastric cancer." (PMID 39104395, 2024). "Finally, we evaluated the expression of TET3 protein in gastric cancer cell lines (NCI-N87, BGC-823, HGC-27) with differing degrees of differentiation." (PMID 39104395, 2024). "Given the significance of TET3, we modulated its expression in the NCI-N87 gastric cancer cell line." (PMID 39104395, 2024). "In our study, only TET1 showed reduced expression in gastric cancer, while TET2 and TET3 increased in cancer tissues, an expression pattern consistent with the TCGA gastric cancer dataset." (PMID 35805009, 2022). "Taken together, we found a possible site-specific methylation for CD148 expression in gastric cancer, with potential regulators TET2 and TET3." (PMID 32201537, 2020).
Glucose intolerance (6 papers, 2022 to 2024). Glucose intolerance (GI) can be defined as dysglycemia that comprises both prediabetes and diabetes. "A noteworthy and worrisome discovery has previously uncovered significant changes in gene expression in oocytes affected by severe T1D, particularly highlighting the implications of TET3 insufficiency to be associated with glucose intolerance in offspring." (PMID 38491313, 2024). "These clinical advances raise questions about the translatability of the recent finding of maternal inheritance of glucose intolerance via oocyte TET3 insufficiency." (PMID 38491313, 2024). "Taken together, this study identifies TET3 as a key epigenetic factor in the oocyte responsible for transmitting glucose intolerance from mother to offspring." (PMID 36209147, 2022). "Moreover, injection of exogenous Tet3 mRNA in oocytes from hyperglycemic mice was sufficient to rescue the maternal effect on glucose intolerance in the offspring." (PMID 36209147, 2022).
hepatocellular carcinoma (6 papers, 2015 to 2025). A malignant tumor that arises from hepatocytes. "The decrease expression of Tet2 and Tet3 in hepatocellular carcinoma cells was accompanied by the decrease level of 5hmC, and they were up-regulated in the addition of 5-AZA." (PMID 36430235, 2022). "The data presented here indicate that a drop of TET2 and TET3 expression and activity as well as IDHs is impaired in hepatocellular carcinoma with a concomitant reduction of 5hmC." (PMID 26366235, 2015). "Moreover, Sajadian underscore the impaired expression and activity of TET2 and TET3 in hepatocellular carcinoma, further validating our analysis." (PMID 39104395, 2024). "In our study, we clearly found that only TET2 and TET3 genes are significantly reduced in HCC tissue and in hepatocellular carcinoma cell lines." (PMID 26366235, 2015). "Another study uncovered the critical role of TET3-mediated DNA hydroxymethylation of ZMIZ1, a mechanism that activates the Notch1/c-Myc axis, alters macrophage polarization status, and ultimately affects hepatocellular carcinoma progression." (PMID 41299461, 2025). "Our data clearly show that the expression and activity of TET2 and TET3 proteins but not TET1 are impaired in hepatocellular carcinoma leading to the reduction of 5hmC in HCCs." (PMID 26366235, 2015). "The researchers, however, found no change in TET3 expression in hepatocellular carcinoma compared to normal liver samples." (PMID 26366235, 2015). "We found that TET2 expression was up‐regulated in serum‐starved hepatoma cells, while the expression of TET1 and TET3 did not change." (PMID 37752791, 2023). "A study of hepatocellular carcinoma observed decreased expression of TET1, but not TET2 and TET3." (PMID 29849955, 2018).
prostate carcinoma (6 papers, 2016 to 2025). A carcinoma that arises from epithelial cells of the prostate gland. "However, some researchers have reported that upregulated TET3 expression in prostate cancer patients might be associated with poor prognosis." (PMID 37325635, 2023). "Studies on prostate cancer have confirmed that the interaction between TET3 and AHR can influence the expression of various factors." (PMID 37718440, 2023). "Analysis of the TME in prostate cancer patients showed differentially expressed NSUN6, TET1 and TET3 in M1 and M2 macrophages." (PMID 37325635, 2023). "The biological significance of miR‐200c and miR‐141 expression in prostate cancer cells was assessed by a series of in vitro bioassays and the effect on proposed targets DNMT3A and TET1/TET3 was investigated." (PMID 27198154, 2016). "The dysregulation of HERV activation restriction genes has also been found in other cancers, such as the overexpression of TET1, TET3, and APOBEC3B but downregulation of APOBEC3C, 3G, 3D, 3H, and C2 in prostate cancer, and different cancers may involve different activation restriction genes." (PMID 37509325, 2023).
Autoimmunity (5 papers, 2021 to 2025). The occurrence of an immune reaction against the organism's own cells or tissues. "Mice with B‐cell‐specific Tet2 knockout appeared to experience a minor effect in B‐cell development, but together with Tet3 deficiency it caused spontaneous hyperactivation of both B and T cells and autoimmunity." (PMID 39722652, 2025). "A series of studies have demonstrated that Tet2/Tet3 DKO in B cells is a key factor that contributes to the spontaneous hyperactivation of both B and T cells, autoantibody production and autoimmunity development." (PMID 34222235, 2021). "Animal studies suggest that Tet2- and Tet3-mediated chromatin modification participated in the repression of CD86 on self-reactive B cells, a mechanism that may contribute to autoimmunity prevention." (PMID 37048133, 2023). "Additionally, given that CD86 overexpression in tolerant B cells caused them to break tolerance, collectively, Tet2 and Tet3 are essential for CD86 expression suppression in self-tolerant B cells and play important roles in autoimmunity prevention." (PMID 34222235, 2021).
B cell lymphoma (5 papers, 2016 to 2023). "One study reported that Tet2 and Tet3 deficiency increases G-quadruplex and R-loop formation and promotes B-cell lymphoma development in mice." (PMID 37363169, 2023). "Rather, combined TET2 and TET3 loss‐of‐function in germinal centre B cells favours C‐to‐T and G‐to‐A transition mutagenesis, a finding that may be of significance for understanding the aetiology of B‐cell lymphomas evolving in conditions of reduced TET function." (PMID 31120187, 2019).
colorectal cancer (5 papers, 2014 to 2024). A primary or metastatic malignant neoplasm that affects the colon or rectum. "We also showed that expression levels of DNMT1 and TET3 are associated and correlated within the inflamed tunica muscularis of colorectal cancer tissue as well as in the jejunal tunica muscularis of both Dnmt1-WT and Dnmt1-KO mice." (PMID 29700293, 2018). "Somatic-cell cancers such as ovarian, head/neck squamous cell carcinoma, gastric, and colorectal cancers have been implicated with TET3 disruption but the mechanistic influence of TET3 remains unclear." (PMID 39149518, 2024). "In colorectal cancer, reduced transcript level of TET3 was observed in cancerous tissue compared with their histopathologically unchanged counterparts." (PMID 32209730, 2020).
Insulin resistance (5 papers, 2022 to 2025). Increased resistance towards insulin, that is, diminished effectiveness of insulin in reducing blood glucose levels. "For instance, mice with skeletal muscle–specific Tet3 ablation show normal development and metabolism and are even resistant to diet-induced insulin resistance." (PMID 40794443, 2025).
Intellectual disability (5 papers, 2021 to 2024). "In humans, TET3 deficiencies were further recently linked to intellectual disabilities and growth retardation." (PMID 34215750, 2021). "Weakened catalytic activity of TET3 is related to intellectual disability and abnormal growth, implying a crucial function of TET3 in development." (PMID 39334883, 2024).
leiomyoma (5 papers, 2016 to 2023). A well-circumscribed benign smooth muscle neoplasm characterized by the presence of spindle cells with cigar-shaped nuclei, interlacing fascicles, and a whorled pattern. "A similar observation was found for TET3 in uterine leiomyomas, a H19—let-7—TET3 axis was identified for methylation regulation of fibroid-promoting gene and to drive proliferation of leiomyoma cells." (PMID 36533073, 2022). "Recent work suggests that DNA methylation in leiomyomas is mediated by the long non-coding RNA H19, which regulates TET3 expression." (PMID 32094355, 2020). "Small interfering RNA (siRNA) knockdown of either TET1 or TET3 leads to decreased proliferation of primary leiomyoma cells, suggesting a potentially important role of TETs in the pathogenesis of fibroids." (PMID 31089260, 2019). "In this report we show that H19 expression is significantly increased in fibroids as compared with normal myometrium, and that H19 functions to promote leiomyoma cell proliferation and expression of MED12, HMGA2, TET3, and ECM-remodeling genes." (PMID 31089260, 2019). "According to our previous findings, H19 expression was shown to be much higher in UFs than in the normal myometrium; H19 stimulated leiomyoma cell proliferation as well as the expression of MED12, HMGA2, ten-eleven translocation 3 (TET3), and ECM remodeling genes." (PMID 37507391, 2023). "Furthermore, TET1 and TET3 protein levels are higher in uterine leiomyoma, and TET1 or TET3 knockdown decrease cell proliferation of leiomyoma cells." (PMID 27557497, 2016).
myeloid malignancies (5 papers, 2016 to 2022). "Two recent studies suggested that TET3 is required for the growth of human TET2MTAML cells, suggesting that IDH1/2 mutations might selectively repress TET2MT myeloid malignancies by 2HG-mediated inhibition of TET3." (PMID 36203205, 2022). "These phenotypes are consistent with prevalence of myeloid disorders and malignancies linked to Tet2 loss in adult mice as well as with onset of more robust and aggressive myeloid malignancies associated with inducible combined deletion of Tet2 and Tet3 in adult mice." (PMID 35235365, 2022).
pancreatic cancer (5 papers, 2021 to 2025). "Our results suggest that the KRAS/Lin28B axis drives the let‐7i/TET3 pathway to maintain the stemness of pancreatic cancer cells." (PMID 33107691, 2021). "Thus, KRAS maintains the stemness of pancreatic cancer cells through a unique Lin28B/let-7i/TET3 feedback loop." (PMID 35651786, 2022). "The increased TET3 will activate Lin28B for maintaining the stemness of pancreatic cancer." (PMID 35651786, 2022). "Therefore, our results illuminate the distinct mechanism of Lin28B nuclear translocation and suggest that the KRAS/Lin28B axis drives the let‐7i/TET3 pathway to maintain the stemness of pancreatic cancer cells." (PMID 33107691, 2021). "The KRAS/Lin28B axis maintains stemness of pancreatic cancer cells via the let‐7i/TET3 pathway." (PMID 33107691, 2021). "Targeting the TET3/GATA6 axis in combination with ferroptosis and epigenetic modulators offers a promising strategy to overcome therapeutic resistance in aggressive pancreatic cancer." (PMID 40567112, 2025).
viral infection (5 papers, 2021 to 2025). "To verify the functionality of TET3 in virus infection, we generated Arabidopsis tet3 mutant by designing a CRISPRCas9–mediated TET3 gene deficiency, termed tet3c." (PMID 35310653, 2022). "To understand the genetic correlation and biological significance of TET distribution during virus infection, we examined the ability of intact TET3 or TET3 variants on the cell-to-cell movement of tobacco rattle virus (TRV) in tobacco leaves." (PMID 35310653, 2022). "During virus infection, the intact TET3 protein enhanced but GCCK/RP motif or cysteine residues-deficient TET3 variants abolished the cell-to-cell movement capability of virus." (PMID 35310653, 2022). "The same mechanism applies to TET3 regulated inhibition of type I interferon production during viral infection or poly(I:C) stimulation." (PMID 34394088, 2021). "Upon IAV infection, some modifications or changes were created in both SPHK2 and TET3, leading to SPHK2’s accumulation in the nucleus and the interaction of SPHK2-HDAC1 complex with TET3, subsequently the specific binding of the IFN-β promoter recruited by TET3 in response to viral infection." (PMID 36070294, 2022). "To prove the hypothesis that TET3 promotes viral infection, we inoculated Arabidopsis leaves with cucumber mosaic virus (CMV)." (PMID 35310653, 2022). "TET2 and TET3 have been shown to inhibit proinflammatory cytokine expression by recruiting HDAC1/2 to the promoters of cytokine encoding genes during bacterial and viral infection, respectively." (PMID 34394088, 2021). "TET3 in macrophages actually suppresses type I IFN production, so reducing TET3 is not expected to dampen the host’s ability to fight viral infections." (PMID 40794443, 2025). "Specially, TET3 can function in a DNA demethylation-independent manner and binds to the IFN-β promoter and leads to the recruitment of HDAC1 to the IFN-β promoter, consequently inhibiting IFN-β transcription under viral infection." (PMID 36070294, 2022).
colon cancer (4 papers, 2018 to 2025). "5hmC is increased in metastatic liver tissue relative to the primary colon tumour and expression of TET2 and TET3 is negatively correlated with risk for metastasis in patients with CRC." (PMID 40241172, 2025). "Quantitation of protein showed that the increases in DNMT1 and TET3 were significant in the inflamed smooth muscle from anal or colon cancer samples." (PMID 29700293, 2018). "We do not have RNA from our metastasis samples, but a publicly available RNAseq dataset for colon cancer with matched liver metastasis confirmed TET2 and TET3 to be the more abundant TET transcripts in colon and liver metastasis." (PMID 40241172, 2025). "Among the TET family (TET1, TET2, and TET3), the suppression of TET1 expression is characteristic of colon cancer." (PMID 39982248, 2025).